INS (insulin)
Diseases named in the same sentence as INS in open-access papers (continued):
Sharing a sentence is not in itself a finding about the gene and the disease.
Glucose intolerance (continued). "Thus, gut exposure to air pollution particles induced glucose intolerance and impaired insulin secretion also in a “prestressed” condition involving HFD/STZ, while lung exposure did not." (PMID 36895000, 2023). "In a more recent study, it was shown that such selenoprotein-F knockout mice developed glucose intolerance and insulin reduction and that the deleterious effects induced by a high-fat diet (obesity, hyperglycemia, glucose intolerance, and hepatic steatosis) were markedly increased." (PMID 37373256, 2023). "Moreover, it is suggested that CIH has a fundamental role in various metabolic impairments, including impairments in insulin sensitivity, higher fasting insulin and glucose levels, reduced beta cell function, and glucose intolerance." (PMID 37058537, 2023). "When maternal insulin production is insufficient to compensate for the insulin-resistant condition, glucose intolerance develops, which may increase the chance of developing GDM." (PMID 36631877, 2023). "This is correlated with reduced CMRglc values, and we hypothesize that the insulin-independent glucose intolerance effected by Aβ represents a surrogate marker of the glucose which is not used in the CNS, due primarily to dysfunctional GLUT1." (PMID 37163733, 2023). "In one large study (n = 25 women with TS), early defects in insulin secretion were accompanied by heightened insulin sensitivity, suggesting that perhaps glucose intolerance progresses over time in TS as insulin secretory capacity falls and insulin resistance becomes apparent." (PMID 36875465, 2023). "Inflammation and oxidative stress caused by BPA exposure may also favor disruptive effects on glucose metabolism leading to glucose intolerance by disruption of insulin signaling in adipose tissue." (PMID 38008036, 2023). "In addition, ad libitum glycemia rhythm was abolished in CJL-subjected mice and an IPGTT shows glucose intolerance in dark, with increased insulin release at both light and dark periods." (PMID 37125029, 2023). "Inflammation and oxidative stress may further aggravate carbohydrate metabolism disorder including disrupted insulin signaling in adipose tissue and glucose intolerance." (PMID 38008036, 2023). "For T2D, one previous study had indicated IL-1β could impair insulin secretion, contributing to the development of glucose intolerance and T2D." (PMID 37113481, 2023). "Furthermore, this dose has been shown to affect metabolism including increased BW and altered glucose homeostasis (glucose intolerance, decrease insulin sensitivity and lipid haemostasis) in previous rodent models of gestational exposure." (PMID 37291156, 2023). "In addition, AM2−/− mice develop glucose intolerance with elevated serum levels of Insulin during pregnancy compared to the AM2+/+mice." (PMID 36875025, 2023). "It has been broadly reported that VFA, but not total adiposity or SFA, is associated with glucose intolerance, suggesting an insulin-resistant state." (PMID 38066623, 2023). "Mice deficient for the extracellular domain of GPIbα displayed glucose intolerance associated with reduced glucose‐stimulated insulin levels while insulin sensitivity was not altered." (PMID 37490001, 2023). "Therefore, future studies of gestational or developmental eTRF should examine islet size, pancreatic beta cell mass, and insulin secretion to investigate the mechanism of offspring glucose intolerance more conclusively." (PMID 37808966, 2023). "On the basis of separate measures of glucose and insulin AUC, our data could suggest greater glucose intolerance during MEB compared to COMP." (PMID 37513677, 2023). "However, male offspring from dams that were fed a HF failed to respond to a supra-physiological glucose load suggesting mild glucose intolerance presumably due to altered insulin secretion." (PMID 37960344, 2023). "Thus, the deletion of p85α in β cells results in glucose intolerance due to impaired insulin secretion." (PMID 37628845, 2023).
Glucose intolerance (continued). "There is evidence that, prior to 20 weeks gestation, fetal insulin production may be impaired by maternal glucose intolerance." (PMID 37176607, 2023). "Glucose intolerance arises from defects in glucose-stimulated insulin secretion from the pancreatic β-cells, dampened responses to insulin in insulin-sensitive tissues such as the liver, adipose tissues or skeletal muscles, or a combination of defects in both insulin secretion and sensitivity." (PMID 37223028, 2023). "GLP-1R agonists are a class of drugs targeting the incretin system that are now being investigated as potential medications to treat GDM, due to numerous recent publications showing their beneficial effects on insulin sensitivity and glucose intolerance during pregnancy." (PMID 37590249, 2023). "In current study, ATF6−/− mice showed glucose intolerance and impaired insulin sensitivity." (PMID 38007457, 2023). "We reveal that platelets specifically interact with the microvasculature of pancreatic islets and that genetic or pharmacological interference with major platelet adhesion/activation pathways consistently results in decreased glucose‐induced insulin release leading to glucose intolerance." (PMID 37490001, 2023). "Several factors may contribute to this condition, but the reduction of the beta-cell mass, the impairment of the insulin secretion and resistance, and the induction of glucose intolerance may play a pivotal role." (PMID 37250653, 2023). "Polyphenolic ingredients regulated at blood sugar level after meals and improved glucose intolerance by facilitating insulin response and reducing the secretion of hormones such as glucose-dependent insulinotropic polypeptide (GIP) and glucagon-like polypeptide-1 (GLP-1)." (PMID 37521997, 2023). "We observed that EECΔCol mice have a blunted 15-minute GLP-1 and Insulin response to glucose challenge, which may be sufficient to explain the glucose intolerance observed in weight-matched mutant mice, akin to the phenotype of GcgΔCol mice." (PMID 37461519, 2023). "In addition, βS2KO mice exhibited islet ER stress and mild age-dependent glucose intolerance and had reduced in vivo insulin levels before and after glucose stimulation." (PMID 37537395, 2023). "One previous study found that the absence of IGF1R in beta cells in mice caused glucose intolerance and deficiency in insulin secretion." (PMID 38274107, 2023). "ME8DKO mice show glucose intolerance without changes in body weight or insulin sensitivity, as found in each singly deficient mice." (PMID 36803984, 2023). "Thus, the insulin insensitivity and glucose intolerance observed in AdHk2KO mice cannot be explained solely by impaired glucose uptake in adipose tissue." (PMID 36920797, 2023). "The latest research on the effect of Cdc42 deletion in pancreatic β-cells and hypothalamus showed that Rip-CDC42cKO mice exhibited glucose intolerance, a significant decrease in glucose-induced insulin secretion in isolated islets, and decreased insulin sensitivity in peripheral tissues." (PMID 38068822, 2023). "Moreover, similar to our observation in β-Dner cKO mice, NCAM-/- mice showed glucose intolerance and defective insulin secretion, which were attributed, at least in part, to impaired actin remodeling." (PMID 37223028, 2023). "Enrichment for oestrogen response genes matched with the more severe glucose intolerance observed in βp65KO female mice and, of interest, oestrogen has been reported to play a glucose-lowering role in humans and mice by enhancing beta cell insulin secretion." (PMID 37311878, 2023). "Consistently, decreased insulin sensitivity and glucose intolerance could be observed in mice with WAT‐specific HIF1α overexpression." (PMID 37303813, 2023). "In addition, OT and OT analogs also improved insulin secretion and attenuated glucose intolerance in diabetic mice." (PMID 37375670, 2023).
Glucose intolerance (continued). "Additionally, it is present as trimers, hexamers, and high molecular weight multimers; the latter form is the more active in improving insulin sensitivity and protecting against glucose intolerance." (PMID 37060190, 2023). "Consequently, the Nnt mutation has been linked to metabolic phenotypes observed in 6J mice, including impaired insulin secretion and glucose intolerance." (PMID 37531359, 2023). "In addition, the HFD caused glucose intolerance, and decreased the islets’ GSIS and insulin content." (PMID 36725880, 2023). "Glucose intolerance and insulin sensitivity were significantly improved by HMBA." (PMID 37984341, 2023). "Interestingly, when challenged with pregnancy, AM2−/− mice became developed elevated serum triglycerides with impaired glucose intolerance accompanied with elevated levels of fasting serum insulin compared to the wild type littermates." (PMID 36875025, 2023). "Importantly, data exist showing that maternal glucose intolerance can impact the production of fetal insulin prior to 20 weeks gestation." (PMID 37176607, 2023). "Oat fiber reduces the glucose intolerance and insulin sensitivity in individuals with MS." (PMID 37374119, 2023). "Indeed, HFD/STZ mice exposed to particulate air pollutants via gavage developed glucose intolerance at an earlier timepoint compared to mice on standard diet, most likely due to an inability to compensate for the increased insulin demand." (PMID 36895000, 2023). "We suggest that circulating sEVs regulate maternal glucose homeostasis in pregnancy and may contribute to the attenuated islet insulin secretion and more pronounced glucose intolerance in GDM as compared with healthy pregnancy." (PMID 36239315, 2022). "When viewed in relation to the ambient glucose level, the postprandial insulin response was never greater than that seen in NGT in glucose intolerance, with a deficient and continually worsening response with increasing FPG in T2DM." (PMID 34561756, 2022). "In conclusion, our results suggest that circulating sEVs regulate maternal glucose homeostasis in pregnancy and may contribute to attenuated islet insulin secretion and more pronounced glucose intolerance in GDM compared with normal pregnancy." (PMID 36239315, 2022). "Furthermore, liver-specific MALAT1 knockdown by tail vein injection of si-MALAT1 daily for 10 days decreased blood glucose level, improved glucose intolerance, increased insulin sensitivity and decreased lipid accumulation in the liver of ob/ob mice." (PMID 36555704, 2022). "Moreover, we found that nondiabetic plasma-treated SVFs increased Akt activation following insulin administration and attenuated glucose intolerance in Leprdb/db mice." (PMID 35883204, 2022). "In contrast, and of particular interest, ablation of PIP5K1c in adipocytes in mice fed a HFD ameliorates metabolic abnormalities, including decreased fasting blood glucose levels, improved insulin sensitivity, ameliorated glucose intolerance and ameliorated fatty liver." (PMID 34996482, 2022). "This suggested a potential increasing inability to deal with the ageing-related rise of insulin demand and could justify the glucose intolerance of AtrxKO mice." (PMID 36010860, 2022). "In non-pregnant mice, the same dietary intervention does not cause glucose intolerance, and slightly increases insulin concentrations." (PMID 36520818, 2022). "In addition, the UOX-KO mice showed glucose intolerance and insulin insensitivity compared to the WT mice, as assessed by the GTT or the ITT." (PMID 36177037, 2022). "Significant increments were also observed in the percentage of people with psychosis meeting clinically elevated levels of glucose and insulin, and both HOMA index and TG/HDL ratio, indicating a greater risk for the development of glucose metabolism alterations such as glucose intolerance." (PMID 35971658, 2022).
Glucose intolerance (continued). "This phenomenon is not surprising, provided that subsets of AD patients exhibit certain T2DM features, such as high fasting insulin levels, insulin resistance (i.e., the resistance of tissues in charge of glucose disposal to the actions of insulin), and glucose intolerance." (PMID 36362376, 2022). "Although whole-body PAK1 knockout mice exhibit glucose intolerance and are insulin resistant, the contribution of skeletal muscle PAK1 in particular was unknown." (PMID 35222279, 2022). "rpS6P−/− mice also exhibited glucose intolerance, reduced insulin secretion, and hypoinsulinemia." (PMID 35879299, 2022). "Although the expression of insulin-dependent and insulin-independent GLUTs was increased, a state of glucose intolerance was induced in H9c2 cells, resulting in reduced glucose utilization, which could be significantly amended by insulin treatment." (PMID 36430296, 2022). "The findings of the current study demonstrate the feasibility of a home-based RET program using a telehealth approach in adolescents with glucose intolerance and suggests positive effects on insulin secretion, body composition, and physical fitness in adolescents with CFRD." (PMID 35328985, 2022). "Our study primarily involved Chinese females with normal BMI, healthy and without a predisposition to glucose intolerance, and hence an absence of significant insulin and HOMA-IR changes can be expected." (PMID 35894647, 2022). "Hagen and her team demonstrated in their prospective cohort that impaired insulin secretion seems to be the major mechanism in the development of NODAT after renal transplantation and that normalization of glucose intolerance is associated with improved insulin secretion." (PMID 35510006, 2022). "We speculated that abnormal glucose production derived from dysregulated gluconeogenesis might account for SHBs-induced elevation of glucose levels, glucose intolerance, and decreased insulin sensitivity." (PMID 36394315, 2022). "Moreover, different allelic variations in vitamin D3 metabolism-related genes have been proposed as predictive markers of insulin imbalance and glucose intolerance." (PMID 36091806, 2022). "The insulin reduction observed in RUPP offspring (male pups) could partially explain glucose intolerance." (PMID 36109770, 2022). "Similarly, curcumin treatment attenuated glucose intolerance and boost insulin sensitizing response." (PMID 36248416, 2022). "EA also directly increased glucose-stimulated insulin secretion from isolated islets, suggesting that EA acted directly on pancreatic β cells to exert anti-diabetic activity, thereby stimulating insulin secretion and reducing glucose intolerance." (PMID 35745279, 2022). "Examples include compromised insulin signalling in hepatocytes, elevated free fatty acids, systemic insulin resistance, and glucose intolerance due to constitutively active (CA) IKK expression in the liver brought on by these hazardous substances or the metabolic imbalance." (PMID 36552644, 2022). "Interestingly, VDRKO mice bred on a CD1 background were relatively protected from glucose intolerance during high-fat feeding, despite lower insulin levels." (PMID 35714079, 2022). "During pregnancy, glucose intolerance and insulin sensitivity were evaluated." (PMID 35706903, 2022). "Utilizing a neutralizing antibody against IL-2318,19, we demonstrate that preventative inhibition of IL-23 not only protects against the development of glucose intolerance and insulin insensitivity, but could also dampen the development of NAFLD." (PMID 35301333, 2022). "Furthermore, the glucose intolerance in miR-21βKO mice was accompanied by reduced insulin concentration in the serum after glucose load." (PMID 35729232, 2022). "In addition, Aα4KO mice displayed severe glucose intolerance during an intraperitoneal glucose tolerance test and marked resistance to exogenous insulin upon insulin tolerance testing." (PMID 36241662, 2022).
Glucose intolerance (continued). "Interestingly, the study demonstrated OC−/− mice were obese, with glucose-intolerance due to decreased insulin production and β-cell proliferation, and were insulin-resistant in comparison to wild mice." (PMID 35983511, 2022). "Moreover, nondiabetic plasma-treated SVFs enhanced Akt activation in Leprdb/db mice following insulin administration and attenuated glucose intolerance in Leprdb/db mice." (PMID 35883204, 2022). "Moreover, the model in this study exhibited IR and glucose intolerance, with significant additional defects in insulin-stimulated glucose uptake in skeletal muscle and insulin-mediated suppression of glucose production in the liver." (PMID 35163187, 2022). "In addition, overexpression of the miR-221/222 family was shown to impair insulin production and secretion by β-cells and resulted in glucose intolerance in mice." (PMID 35740314, 2022). "Moreover, FGF9 transgene enhanced the insulin sensitivity and improved glucose intolerance in diet-induced obese FGF9alb-cre mice when compared to the control mice." (PMID 35517790, 2022). "The resultant CD38 knockout mice having human CD38 transgene ameliorated the glucose intolerance and the decreased insulin secretion observed in CD38 knockout mice, suggesting that the observed phenotype in CD38 knockout mice is indeed caused by the disruption of the CD38 gene in pancreatic β-cells." (PMID 35457121, 2022). "In four-week-old male weanling C57BL/6J mice treated with 25 or 50 ppm of sodium arsenite and high-fat-diet (HFD) for 20 weeks resulted in an increased glucose intolerance and decreased insulin secretion in dose-dependent manner compared with mice only exposed to HFD." (PMID 35651975, 2022). "Please note, glucose and insulin were dosed based on body weight, which may potentially worsen glucose intolerance but mask insulin intolerance in wild type mice." (PMID 34747141, 2022). "In contrast, male mice exposed to a physiologically relevant high dose of PFOA had increased fasting glucose levels, mild glucose intolerance, and reduced insulin sensitivity but normal fasting insulin; glucose-stimulated plasma insulin levels were not measured in this study." (PMID 35156417, 2022). "However, in the HSuHF + BJ-treated rats, glucose intolerance and insulin sensitivity were alleviated when compared to the HSuHF group, as reflected by both the lower AUC of GTT (p < 0.05) and significantly higher kITT values (p < 0.001)." (PMID 34959746, 2021). "This non‐intuitive glucose intolerance with insulin sensitivity may be due to low β‐cell mass, leading to impaired effects of glucose clearance, which is also seen in GHR knockout models." (PMID 33755309, 2021). "In fact, only approximately two thirds of the study arms with GIP receptor or GLP-1 receptor KO mice versus wildtype mice showed glucose intolerance accompanied by a reduced insulin response, whereas in approximately a third of study arms these KO mice had normal glucose tolerance." (PMID 34122340, 2021). "Therefore, administration of AME containing rutin, quercetin, kaempferol, acetogenins seems to be effective in diabetic metabolic abnormalities by attenuating blood sugar, reducing glucose intolerance, and enhancing insulin signaling pathway." (PMID 34679681, 2021). "Paternal diabetes induced by low-dose streptozotocin was shown to cause insulitis and impaired insulin secretion in the offspring, while paternal HFD-induced prediabetes caused filial glucose intolerance and insulin resistance that was transmitted up to the second generation." (PMID 33419045, 2021). "However, the function of vaspin is to improve glucose intolerance and insulin sensitivity and reduce the synthesis of pro-inflammatory cytokines." (PMID 33807959, 2021). "However, when challenged with an HFD, only female βOgtOE (homozygous) Hz mice developed a mild glucose intolerance, despite increased insulin secretion and normal β-cell mass." (PMID 34685781, 2021).